LCN2 (lipocalin 2)
Diseases named in the same sentence as LCN2 in open-access papers (continued):
Sharing a sentence is not in itself a finding about the gene and the disease.
cancer (continued). "Top five up-regulated genes in malignant tumours were COL11A1, SFRP2, LCN2, COL2A1 and H19, while top up-regulated genes in benign tumours were MMP3, MMP1, AREG, PTHLH and SFRP2." (PMID 30517191, 2018). "More recently, TAM-secreted lipocalin-2 (Lcn2) was found to promote cancer cell dissemination by regulating EMT, resulting in increased cancer cell motility." (PMID 29197379, 2017). "Recent studies demonstrated that LCN2 induces epithelial-mesenchymal transition (EMT) and upregulation of MMP-9 in cancer progression." (PMID 25940797, 2015). "Next, we examined the expression of LCN2 in HepG2, A375, MCF-7, and HOS human cancer cell lines cultured under hypoxic conditions." (PMID 25467539, 2014). "Lipocalin 2 (LCN2) is a small secreted protein and its elevated expression has been observed in pancreatic as well as other cancer types." (PMID 23056397, 2012). "Based on the single-cell RNA-sequencing analysis of CSF in five patients with breast cancer and NSCLC, a higher expression of the iron-binding protein lipocalin-2 and its receptor, SCL22A17, was identified in cancer cells as a result of the macrophage cytokine response." (PMID 38558729, 2024). "Additionally, the conditioned medium from c-MET-overexpressing cells significantly induced neutrophils to secrete lipocalin 2 (LCN2), which in turn promoted the self-renewal of cancer stem cells, a process reported to induce immunosuppression." (PMID 39201787, 2024). "The inhibition of Lcn2 and MC4R improved cancer-induced anorexia as well as CAC symptoms." (PMID 37222464, 2023). "When cancer cells are co-cultured with macrophages (THP-1 cells), the expression of LCN2 and MMP-9 has been found to be induced in ADAM8-KO cells, indicating that macrophage signal transduction can override ADAM8-driven intracellular signal transduction in PDAC cells." (PMID 36910158, 2023). "This is attributed to the fact that Lcn-2 is also able to promote epithelial-to-mesenchymal transition (EMT) and bind to matrix metalloprotease 9 (MMP9), thereby modulating the metastatic phenotype of cancer cells." (PMID 37958332, 2023). "The interaction of LCN2 with MMP9 plays a crucial role in modulating the metastatic phenotype of cancer cells, and this interaction correlates with the aggressive behaviour of neoplastic cells in several types of cancer." (PMID 37753805, 2023). "This process of non-transferrin-mediated iron uptake, involving Lcn-2 as a key player, has been shown to be involved in cancer progression." (PMID 37958332, 2023). "Elevated levels of LCN2 were observed in serum samples from cachectic patients compared with non-cachectic cancer patients." (PMID 36428623, 2022). "Compared with cancer patients with no cachexia, cachectic cancer patients had significantly higher level of LCN2." (PMID 36428623, 2022). "Furthermore, gene ontology analysis (STRING) was performed for each protein cluster to assess the matching of proteins with the KEGG pathways to identify the role of LCN2, SLC22A17, and MMP9 genes in cellular processes and cancer pathways." (PMID 36211450, 2022). "Knockdown of LCN2 is known to affect tumorigenic markers and the EMT process in various cancers." (PMID 35053376, 2022). "Elevated levels of LCN2 mRNA and protein have been observed in various types of cancers including CRC, suggesting that LCN2 may serve as a biomarker for cancer." (PMID 35470375, 2022). "Serum concentrations of CCL20 and LCN2 were remarkably elevated in cancer groups in comparison with noncancer groups." (PMID 35308139, 2022). "By specifically knocking down expression of two iron metabolic genes, FPN and LCN2, with the DMP-controlled CRISPR/Cas13a and microRNA (miRNA) in cancer cells, the FeNP treatment induced dramatic ferroptosis in a wide variety of cancer cells that represent various hematological and solid tumors." (PMID 34493724, 2021).
cancer (continued). "High levels of monomeric forms of LCN2, MMP-9, and LCN2-MMP-9 heterodimers are secreted into the extracellular space, and their levels seem to correlate with the aggressive behavior of neoplastic cells in several types of cancer." (PMID 32575507, 2020). "Although the function of lipocalin-2 is not well defined but its expression is correlated with progression and metastasis of majority of these cancers." (PMID 33473259, 2020). "The BAMBI (Vanhara and Souček, 2013), LCN2, F13A1, CDKN2A, SLIT2, and CLU were reported to individually play a role in cancer development and progression." (PMID 33585439, 2020). "Combination therapies targeting LCN2, iron-level regulation, and MMP-9 activity could produce synergistic cancer cell death." (PMID 32575507, 2020). "In conclusion, we found that expression of the individual genes CRABP1 and LCN2 may be useful biomarkers in DTC, able to improve FNAB differential diagnosis of benign versus malignant tumours." (PMID 29321030, 2018). "LCN2 (lipocalin 2, also known as NGAL, 24p3, uterocalin, or siderocalin) is a secreted protein that is induced in response to stress and injury and is overexpressed in many types of cancer." (PMID 28467300, 2017). "Recently, the oncogenic role of LCN2 has been described in severe cancers, with higher LCN2 expression in cancerous cells compared to non-cancerous cells." (PMID 27782193, 2016). "Lipocalin-2 (LCN2), belonging to the lipocalin superfamily, was originally deemed as a stress protein, with the oncogene role of LCN2 later being explored in a variety of cancers, including CCA." (PMID 27529229, 2016). "LCN-2 expression is an intrinsic specific property for LST cancer and does not depend on specific recruitment of other hematopoietic or mesenchymal components." (PMID 27339395, 2016). "Moreover, T3-mediated regulation of LCN2 occurred via the Met/FAK cascade and suppression of E-cadherin, leading to cancer cell progression." (PMID 25940797, 2015). "LCN2 stabilizes the proteolytic enzyme matrix metalloprotease-9 (MMP-9) by forming a heterogeneous complex, thereby preventing autodegradation and promoting metastasis of cancer cells." (PMID 26131602, 2015). "Furthermore, LCN2 expression is abundant in neutrophils and in a distinct subpopulation of fibroblasts, suggesting that its role in modulating the TME extends beyond cancer cells." (PMID 40472740, 2025). "However, it remains unclear whether it is less important that LCN2 levels are inherently high or low, and more relevant how these basal expression levels change during interactions with the TME or other cancer cells." (PMID 41303420, 2025). "Additionally, IL-22 upregulates expression of Erk1/2-independent genes such as Discoidin domain receptor tyrosine kinase 2 (DDR2), Lipocalin 2 (LCN2), and Leucine-rich alpha-2-glycoprotein 1 (LRG1), known for their involvement in the modulation of specific cancer hallmarks." (PMID 40806452, 2025). "Additionally, an analysis of cancer stages revealed a significant correlation between the expression levels of SLC3A2, BSG, SLC7A5, SLC7A6, LCN2, and SLC7A9 and the pathological stages of ACC, with p-values of 0.28, 0.468, 0.00799, 0.0237, 0.0359, 0.264, 0.193, 0.81, and 0.0246, respectively." (PMID 40566559, 2025). "Based on the observations detailed above, we believe that is worth following up on the role of PARylation in the regulation of LCN2, MIF, and PAI-1 expression as it may contribute to the anticancer effect of PARylation of various different types of cancer with high abundance of infiltrating MΦs." (PMID 38612413, 2024).
cancer (continued). "LCN2 could affect EMT process by regulating MMP protein expression in GC, and a close relationship between MMP protein expression and SPARC expression has also been found in other cancers." (PMID 39424639, 2024). "In addition, EGR1 and LCN2, which are known to instigate metastasis and angiogenesis, exhibited down-regulation, insinuating that Lipo-ICG phototherapy could counteract cancer metastasis." (PMID 38399278, 2024). "Other studies not related to cancer research also pinpoint the importance of Lcn-2 in apoptosis." (PMID 37958332, 2023). "Importantly, adhesion to collagen I or fibronectin matrices, which are crucial for cancer cell migration and matrix adhesion, were inhibited using non-iron-binding Lcn-2." (PMID 37958332, 2023). "However, the potential benefit of targeting LCN2 has not been applied to any cancer because of contradictory reports about the role of LCN2." (PMID 35705840, 2022). "Lcn2 levels are usually higher in many types of cancers (not the case in this study), which might prevent these results from being translated to other tumor types." (PMID 35785195, 2022). "CXCL1, LCN2, S100A8, and IDO1 may play essential roles in cancer progression." (PMID 34306038, 2021). "Herein, we summarize the cellular and molecular mechanisms of CNS dysfunction during cancer cachexia with a focus on inflammatory, autonomic and neuroendocrine processes and end with a discussion of recently identified CNS mediators of cachexia, including GDF15, LCN2 and INSL3." (PMID 34439145, 2021). "For example, exposure to halogenated agents increased Lipocalin 2 expression over a prolonged period of time, and this over-expression also promotes cell migration and invasion through activating ERK signaling to increase SLUG, whereas knockdown suppresses the growth and invasion of cancer cells." (PMID 34299272, 2021). "Furthermore, despite the finding that LCN2 expression was correlated with immunity and clinical survival in human cancers, we were not sure that LCN2 influenced clinical survival via immune pathway." (PMID 33425761, 2020). "In addition, LCN2 expression was notably correlated with the infiltration levels of CD4+T cells in 13 cancer types, B cells in 12 cancer types, CD8+T cells in seven cancer types, macrophages in 10 cancer types, neutrophils in 12 cancer types, and dendritic cells in 20 cancer types." (PMID 33425761, 2020). "Interestingly, a recent study reports that in the metastatic microenvironment of cerebrospinal fluid, macrophages do not express lipocalin-2 but rather produce inflammatory cytokines that induce lipocalin-2 expression in cancer cells." (PMID 33679721, 2020). "Thus, the heterogeneity of cancer might explain the apparent different role for ITGB4 and LCN2 in PCa." (PMID 30931931, 2019). "Furthermore, TAMs can facilitate cancer cell migration by activating EMT, for example upon release of lipocalin-2 (LCN2), TNF-α, IL-8, IL-6, and TGF-β1, which operate via activation of different EMT-promoting molecular pathways (e.g., Gas6/Axl-NF-κB, JAK2/STAT3/Snail, and PI3K/Akt)." (PMID 30200242, 2018). "Moreover, LCN2 enhanced cell invasion via the EMT pathway, leading to cancer cell progression." (PMID 26840566, 2016). "However, it is not known whether cancer cells acquire iron directly from macrophages or from culture medium that contains ~6 μM iron after being stimulated by LCN2." (PMID 39201626, 2024). "Moreover, lipocalin 2 (LCN2) inhibits ferroptosis by limiting iron uptake, while aconitase 1 (ACO1, also known as IRP1) and iron responsive element binding protein 2 (IREB2, also known as IRP2) promote ferroptosis in cancer cells by regulating the translation of iron metabolism-related protein." (PMID 34742351, 2021). "However, no details about the iron-load of cancer cell-expressed Lcn-2 are available at the moment." (PMID 34069743, 2021). "However, the precise role of LCN2 in cancer has not been completely defined." (PMID 23056397, 2012).
cancer (continued). "Of these, LCN2 and solute carrier family 22 member 17 (SLC22A17) were exclusively expressed in cancer cells and not in macrophages." (PMID 41303420, 2025). "While megalin does not distinguish between apo and holo-forms of LCN2, SLC22A17 seems to be able to discriminate between the two and selectively mediate apoptosis and iron uptake in cancer cells." (PMID 33799862, 2021). "However, the DNA methylation regulation of LCN2 and SLC22A17 has not been sufficiently investigated in cancer." (PMID 36211450, 2022). "However, in SCA patients, the effect of PBK, LCN2 and CCNA1 expression on cancer progression was not statistically significant (p > 0.05)." (PMID 32693821, 2020). "Although the involvement of the NF-κB/snail signaling pathway in promoting metastasis/invasion through EMT has been shown in vivo and in vitro, the regulation of LCN2 in the NF-κB/snail signaling pathway-induced metastasis and EMT in cancer had not been reported." (PMID 27912767, 2016). "It was reported that LCN2 activates cAMP-mediated signaling in bone cells, while increased cAMP signaling may inhibit osteoblast differentiation by decreasing BMP pathway signaling, which indicates the negative effect of cancer-derived LCN2 on osteogenesis." (PMID 36897488, 2023).
infection (349 papers, 2007 to 2026). The state of being infected such as from the introduction of a foreign agent such as serum, vaccine, antigenic substance or organism. "LCN2, also known as neutrophil gelatinase-associated lipocalin (NGAL), is a novel circulatory adipokine that is significantly upregulated during inflammation or infection." (PMID 41191121, 2025). "From the host perspective, temporal regulation of known immune-associated proteins, including eosinophil peroxidase and lipocalin-2, along with suppression of lipoproteins, demonstrated infection- and time-dependent host remodeling." (PMID 41061967, 2025). "Next, to evaluate a connection between host immune system activation and survival, we normalized protein abundance for infection-associated host proteins and observed a substantial increase in lipocalin-2, cathepsin G, and haptoglobin at 4 dpi for mouse #6." (PMID 41061967, 2025). "HRSV infection has been previously shown to cause an increase in the expression of fecal lipocalin-2, which was also associated with low-grade colon inflammation 7 days post-infection." (PMID 38404579, 2024). "The protein products encoded by LTF and LCN2 genes were prominently found in the secondary granules of neutrophils and are considered innate immune proteins to fight infection." (PMID 38912048, 2024). "Lcn2 has higher affinity for siderophores than Lcn1 and it is considered an acute‐phase protein because it is highly produced during infection causing inflammation." (PMID 36857468, 2023). "CP and LCN2 are neutrophil associated host factors involved in this process with CP being one of the most abundant immune proteins at sites of infection." (PMID 37358277, 2023). "Due to the high susceptibility of Lcn2 mice to enterobacteriaceae like E. coli, this pathway appears to be particularly significant in these infections." (PMID 37946846, 2023). "LCN2 is an acute phase molecule released by various tissues in the body that has been linked to injury, infection, and overall inflammation." (PMID 38107410, 2023). "NGAL, also known as lipocalin-2, is an adipokine associated with various processes including metabolic homeostasis, apoptosis, infection, immune response, and inflammation." (PMID 35806888, 2022). "The effects of LCN2 on the outcome of infection has been interrogated for a handful of pathogens using Lcn2-deficient mice." (PMID 36054235, 2022). "There was, however, low levels of LCN2 staining detected in the organs of infected Lcn2-deficient mice, suggesting the existence of a bacterial antigen or induction of an infection-responsive host protein that is cross-reactive with the α-LCN2 antibody." (PMID 36054235, 2022). "Meanwhile, in an infection model of IL-10-deficient mice, LCN2 was shown to prevent spontaneous colitis by enhancing phagocytic bacterial clearance by macrophages." (PMID 36187347, 2022). "Elevated levels of LCN-2 were found in the stool when comparing infected to control mice in all three cohorts, as expected after a pathogenic infection." (PMID 34320343, 2021). "Surprisingly, we also noted that HAMP and LCN2 genes, encoding hepcidin and lipocalin, respectively, two of the main players of hypoferremia in response to infection by other pathogens, remained unaffected after infection." (PMID 34035436, 2021). "LCN2 deficiency was associated with increased body weight loss over nine days after infection, which led to higher mortality in Lcn2-/- mice." (PMID 33905460, 2021). "Our research work suggests that LCN2 is significant in the development of early infection caused by S. japonicum and is of great value for further exploration." (PMID 34616693, 2021). "LCN2, also known as neutrophil gelatinase‐associated lipocalin (NGAL), is released by various cell types and is an attractive biomarker of inflammation, ischaemia and infection." (PMID 34469018, 2021).